HIF1A (hypoxia inducible factor 1 subunit alpha)
Diseases named in the same sentence as HIF1A in open-access papers (continued):
Sharing a sentence is not in itself a finding about the gene and the disease.
cancer (continued). "The emerging role of SDH in cancer, neurological disorders, cell signalling (including stabilization of transcriptional factor HIF-1α), immune response and cardiovascular conditions highlights the need to determine if OAA has a regulatory function." (PMID 27287543, 2016). "Second, we proved that the D-Fe3O4@PMn can target the HIF-1α-expressing cancer cells." (PMID 27976736, 2016). "To uncover the molecular mechanism of miR-592 HCC inhibitory potential, we hypothesized that decreased WSB1 expression by miR-592 would reduce the HIF-1α level in HCC because HIF-1α signaling has been demonstrated to be enhanced by WSB1 in various cancers." (PMID 27153552, 2016). "For example, it has been shown that the activation of HIF1A occurs in carcinoma-associated fibroblasts (CAFs) and it enhances aerobic glycolysis and lactate production, which is converted to pyruvate and utilized for mitochondrial OXPHOS in cancer cells." (PMID 26859576, 2016). "It has also been reported previously that potential resistant mechanism of actions include the activation of the Ras/Raf/MEK/ERK and PI3K/AKT pathway as well as key transcription factors such as NF‐κB and HIF‐1α that play a central role in proliferation and survival of cancer cells." (PMID 26864945, 2016). "Additionally, siRNA-mediated JNK2 knockdown blocked docetaxel-induced HIF-1α degradation and cancer cell death by inhibiting PHD1 activation." (PMID 27263528, 2016). "However, chemotherapeutic drugs targeting VEGF and HIF-1α have limited efficacy against cancer and even cause adverse effects, suggesting that the mechanisms of VEGF- and HIF-1α-related function need to be further elucidated." (PMID 26988756, 2016). "Inhibitors of HIF-1a represent a new tool for improved cancer therapies." (PMID 27456341, 2016). "It is known that HIF1α plays a key role in the reprogramming of metabolism in cancer." (PMID 26743088, 2016). "To test this, we determined whether PHD1 participated in docetaxel-induced HIF-1α degradation in hypoxic cancer cells." (PMID 27263528, 2016). "HIF1α signaling has been linked to EMT and cancer progression." (PMID 27166196, 2016). "In addition, SIRT1 deacetylates and inactivates NF-κB, which plays a beneficial role in cancer survival under stressful conditions like inflammation, and HIF-1α, which promotes cancer survival under hypoxic microenvironment." (PMID 26992208, 2016). "Given that glucose uptake is mainly mediated by glucose transporter 1 (Glut1) in cancer cells, and that Glut1 expression is controlled by hypoxia inducible factor 1a (HIF-1α), we examined expression of Glut1 and HIF-1α target genes in V-ATPase V1E1 depleted cells." (PMID 27384996, 2016). "HIF-1α also plays a key role in the maintenance of cancer stem cells." (PMID 27976736, 2016). "Further, cell viability after treatment of cancer cells with AgNPs under hypoxic conditions was lower in HIF-1α siRNA-transfected cells than in control siRNA-transfected cells, indicating that HIF-1α knockdown enhances hypoxia induced decrease in cell viability." (PMID 26867977, 2016). "And HIF-1α/GPER/VEGF signaling in cancer cells was also activated by copper." (PMID 26958938, 2016). "Secondly, the interaction between PKM2 and HIF-1α is augmented in hypoxic cancer cells." (PMID 26739387, 2016). "There is evidence that HIF-1α can regulate VEGF secretion in cancer cells." (PMID 27581969, 2016). "Moreover, it was demonstrated that HIF-1α-induced upregulation of integrin α5 mediated cancer cell invasion." (PMID 26880989, 2016). "Given the increasing use of HIF-1α inhibitors as an anti-cancer therapy, pharmacological inhibition of aberrantly induced HIF-1α may provide a promising adjunctive medical therapy for patients with small AAA." (PMID 27363580, 2016).
cancer (continued). "Furthermore, siJNK2 effectively reduced PHD1 activation, thereby increasing HIF-1α accumulation and activation and reducing docetaxel-induced cancer cell death under hypoxic conditions." (PMID 27263528, 2016). "This dependence is driven by the activation of MYC and HIF1-α and consequently, targeting pathways regulating glucose/glutamine metabolism may be of relevance for cancer treatment." (PMID 27455839, 2016). "Finally, to evaluate the effects of docetaxel on JNK2/PHD1 signaling-mediated HIF-1α degradation and cancer cell death in vivo, we used a nude mouse xenograft model, created by inoculation of MDA-MB-231 cells into the right flank of BALB/c nude mice." (PMID 27263528, 2016). "Interestingly, treatment of HER-2-overexpressing cell lines with AE significantly reduced the cancer metastasis transcription factors Snail, Slug, Twist, and HIF-1α expression in a dose- and time-dependent manner." (PMID 27391337, 2016). "Furthermore, we discuss the physiological relevance of HIF-1α methylation-dependent regulation of protein stability in human cancers." (PMID 26757928, 2016). "Although the C. elegans study also left open whether the direct regulation of HIFα is conserved among other species, it is known from studies with cancer cells that ROS-dependent HIF-1α activation requires AMPK." (PMID 26942179, 2016). "As a result, mitochondrial cholesterol loading in cancer cells acts as an additional mechanism governing angiogenesis and novel vessel growth via HIF1α stabilization, although this molecular link deserves to be further tested and it is currently under investigation." (PMID 27455839, 2016). "In the present study, in order to find the underlying mechanism of lactobacilli anti-cancer effects, we analyzed the expression of HIF pathway genes and demonstrated that LRS could dramatically down-regulate HIF-1α mRNA expression in the MDA-MB-231 cell line." (PMID 27540529, 2016). "The mammalian transcription factor, Hypoxia-inducible factor-1α (Hif-1α; called Sima or Hifα in Drosophila), regulates a number of target genes that promote various aspects of cancer, including metabolism, angiogenesis, cell survival, drug resistance, and invasive motility." (PMID 27585295, 2016). "Overexpression of both PIN1 and HIF-1α is prevalent in many types of human cancer." (PMID 26784107, 2016). "Our results suggest that hypoxia-mediated autophagy may be a mechanism for the resistance of AgNPs-induced apoptosis and that strategies targeting HIF-1α may be used for cancer therapy." (PMID 26867977, 2016). "This clearly indicates the presence of a feedback loop from HIF-1α to mTOR signaling, which may promote cancer cell survival in the hypoxic niche." (PMID 27821815, 2016). "Here we demonstrated that knockdown of PIG3 by transfecting with specific siRNA could increase the expression of HIF-1α in several human cancer cell lines, including CAKI, FTC-133 and A549." (PMID 27029070, 2016). "Hif-1α is a well-known inducer of LDHA expression in many cancer cell lines." (PMID 27585295, 2016). "Cancer cells are able to increase HIF-1α levels even under normoxic conditions." (PMID 27602585, 2016). "Overexpression of HIF-1α has been found in many types of human cancers and metastasis." (PMID 26872370, 2016). "In this study, we report a regulatory feedback loop between HIF-1α and integrin-linked kinase (ILK) that might underlie the ability of cancer cells to maintain high levels of HIF-1α expression and to promote EMT under hypoxic conditions." (PMID 25821081, 2015). "Indeed, in Drosophila cancer cells suffering from oxygen deprivation the hypoxia-inducible factor Sima/HIF1α translocated into the nucleus and the bnl/FGF promoter resulted activated." (PMID 25762498, 2015). "Thus, in addition to increased protein level via inhibition of proteasomal degradation, HIF-1α expression can be regulated at the transcriptional level via direct or indirect interaction of Sp1 with the HIF1A promoter region in cancer cells." (PMID 26703734, 2015).
cancer (continued). "Resistance to 2-DG has been reported to be mediated by HIF-1α in several cancer cell line models." (PMID 25888489, 2015). "Therefore, in the present study, the effects of bortezomib treatment on the stabilization of HIF-2α and corresponding HIF-2 activity were examined using cancer cell lines known to express both HIF-1α and HIF-2α, and a cancer cell line expressing only HIF-2α." (PMID 26622817, 2015). "Inflammatory cells in the tumor microenvironment may release cytokines to directly stimulate oncogenic signaling in cancer cells, including NF-κB, STAT3 and HIF1α signalings, resultantly promoting cancer survival and proliferation." (PMID 25504436, 2015). "We showed that the anticoagulent protein TFPI1 becomes overexpressed upon exposure to high DOX concentrations, generating a hypoxic-like state by abrogating the expression of an angiogenic profile, and thus inducing the expression of a host of cancer driving proteins including HIF1α." (PMID 26501324, 2015). "Indeed, we previously identified SphK1/S1P signaling as a new canonical modulator of HIF-1 activity under hypoxic conditions owing to a decreased proteasome degradation of HIF-1α subunit mediated by the Akt/GSK3β pathway in various cancer cell models." (PMID 25915662, 2015). "Extending the current knowledge on the action of anti-copper drugs like TEPA, our data indicate that these chemicals may also target HIF-1α/GPER signalling among the multifaceted responses triggered in cancer cells." (PMID 26415222, 2015). "Our unpublished data showed that LMWF could inhibit the proteasome activity in cancer mice, which may be another mechanism elevating the HIF-1α protein level." (PMID 26193287, 2015). "Because of the striking differences in mRNA signals in cancerous and noncancerous cells, we next asked whether this influences overall mRNA levels of CDH1 and HIF1α in tissue sections representing cancer and cancer-free areas." (PMID 26029826, 2015). "For cancer stem cells, the association with HIF-2α is closer than that with HIF-1α." (PMID 25452783, 2015). "HIF-1α has been reported to be over expressed in various malignant tumors and cancer cell lines." (PMID 26526196, 2015). "Further extending these findings, our current results indicate that copper is also able to induce HIF-1α expression, thus providing a new mechanism through which this chemical may be involved in cancer progression." (PMID 26415222, 2015). "Nevertheless, Q6 is the first agent that could promote the autophagic degradation of HIF-1α in hypoxic cancer cells." (PMID 26649750, 2015). "Although increased angiogenesis is a hallmark of cancer, the early pre-leukemic changes are characterized by reduced number of EC, reduced VEGFR1, and -2 signaling, and increased expression of the HIF-1α target genes Pgk1- and Eno1 by CD31+ CD45- Ter119- cells." (PMID 26308666, 2015). "Thus, inhibition of the glycolytic pathway through LDH downregulation or HIF-1α knockdown reprograms cancer cell metabolism towards mitochondrial activities." (PMID 26713093, 2015). "We, therefore, evaluated whether tempol enhances the gene expression via HIF-1α, potentially leading to various applications for cancer gene therapy targeting hypoxic cells." (PMID 26034980, 2015). "Suppressing the expression of HIF-1α is important to evaluate its effect on cancer cells." (PMID 25816356, 2015). "To substantiate that inhibition of the SphK1/S1P pathway could represent a pertinent idea, we evaluated the relevance of inhibiting the extracellular S1P signaling with regard to HIF-1α accumulation under hypoxia in cancer cells." (PMID 25915662, 2015). "Whether HIF-1α regulates the biological behaviors of cancers via SHH signaling is a promising research direction." (PMID 25811359, 2015). "Consequently, HIF-1α is an appealing intracellular target for treating a wide range of hypoxia-related pathologies by targeted cancer therapy." (PMID 26610526, 2015).
cancer (continued). "Furthermore, both Hif-1α and Hif-2α knockout mice exhibit embryonic lethality, indicating non-redundant roles during development and possibly in different types of cancer." (PMID 26009875, 2015). "In agreement with this hypothesis, previous studies have indicated that the inhibition of HIF-1α may be important in cancer therapy." (PMID 25663929, 2015). "Additionally, 17-AAG or deguelin, a novel naturally occurring inhibitor of HSP90, suppresses an increase in the interaction of HIF-1α with HSP90 in cancer cells." (PMID 26569225, 2015). "HIF-1α is a key player in the maintenance of cellular homeostasis under hypoxic conditions through its regulation of the expression of many genes involved in a crucial aspect of cancer biology." (PMID 25649293, 2015). "This MITF318K mutation leads to altered MITF activity and, although the transcription of some melanogenic genes remains unchanged, one consequence of the mutation is transcription of hypoxia-inducible factor 1-alpha (HIF1-α), which provides a growth advantage to cancer cells." (PMID 25670789, 2015). "The regulated markers of HIF-1α, such as glucose transporter type 1 (GLUT1), carbonic anhydrase 9 (CA9) and c-Met, have been found to be highly associated with poor prognosis in various cancers." (PMID 25993275, 2015). "HIF1α is known to be frequently up-regulated and functionally relevant in cancers, therefore HIF1α may be a relevant downstream PPP2R5C target in this pathological context." (PMID 26440364, 2015). "Thus, one of the possible positive effects of GLN supplementation can be making αKT/SC ratio increased in cancer cells which can reduce the overexpression of HIF-1α." (PMID 26583064, 2015). "A major factor influencing cancer metabolism is hypoxia, which is mediated by HIF1α and HIF2α." (PMID 25605240, 2015). "staining of HIF-1α was considerably strong in invasive cancer." (PMID 25723392, 2015). "Therefore, our results identify mechanism by which BRMS1 attenuates cancer cell progression through downregulating HIF-1α and subsequently reducing Snail and TWIST1 expression." (PMID 26520789, 2015). "Furthermore, it was reported that negative regulation of the HIF1A gene by protein arginine methyltransferase 1 in cancer cells involves altered Sp1 protein expression level." (PMID 26703734, 2015). "Because of the important role of HIF1 in cancer, investigation of the regulation of HIF1α might provide novel therapeutic targets." (PMID 26205124, 2015). "Taken together all analyzed data, HIF1A could be a prognostic marker useful for early detection and diagnosis for cancers." (PMID 26715988, 2015). "HIF-1α has been the most studied one because in altered biological processes where the cells are in hypoxic conditions, such as cancer, HIF-1α is overexpressed and translocated to nucleus where it interacts with HIF-1β and p300 cofactors to induce transcription of hypoxia-related target genes." (PMID 26136626, 2015). "Therefore, the miR-373-induced HIF1α-TWIST signaling axis stimulates cancer cell EMT and metastasis." (PMID 26196741, 2015). "Both HIF-1α and ZEB1 have been implicated in cancer metastasis and EMT." (PMID 26057751, 2015). "HIF1α can also be regulated by oxygen-independent pathways, as known to be the case in cancer." (PMID 25884993, 2015). "HIF-1α enhances the hepatic inflammation, fibrosis and cancer by inducing its target genes such as vascular endothelial growth factor, plasminogen activator inhibitor-1, prolyl 4-hydroxylase, alpha peptide 1 (P4HA1), lysyl oxidase (LOX) and endoplasmic reticulum oxidoreductin 1-like (ERO1L)." (PMID 26098428, 2015). "These mutations may lead to an increase in mTOR activity and thus HIF-1α protein synthesis, which may render cancer cells resistant to anti-HIF-1α therapies that affect upstream regulators of HIF-1α synthesis, such as those targeting receptor tyrosine kinases." (PMID 26469226, 2015).
cancer (continued). "Contrary to the expectation that HIF-1α would be activated by glycolytic metabolites in cancer cells, we observed that CD49fhi BCSCs (CD49fhiCD24hi, CD49fhiCD24low) demonstrated reduced expression of HIF-1α gene targets as well as of HIF-1α-inducible glycolytic genes compared with CD49fhi SCs." (PMID 26316122, 2015). "LW6, an HIF-1 inhibitor, was hypothesized to improve resistance to cancer therapy in hypoxic tumors by inhibiting the accumulation of HIF-1α." (PMID 26017562, 2015). "Therefore, lactate from cancer cells functions as an onco-metabolite, stabilizing HIF-1α and stimulating mitochondrial biogenesis in adjacent monocytic cells." (PMID 25938544, 2015). "Of note, HIF-1α also increases the energy metabolism and ATP synthesis in cancer cells." (PMID 26372812, 2015). "The elevation of HIF-1α is pro-oncogenic and lead to cancer development." (PMID 26437434, 2015). "Both HIF-1α protein and HIF1A mRNA are overexpressed in cancer, correlating to poor prognosis." (PMID 26647819, 2015). "Recently, it has been proposed that inhibition of HIF-1α could be a complementary approach for cancer immunotherapy." (PMID 25544770, 2015). "Collectively, these findings suggest that CuSO4 may be involved in the activation of HIF-1α/VEGF transduction signalling in cancer cells." (PMID 26415222, 2015). "The findings that HIF-1α enhances the hepatic inflammation, fibrosis and cancer, and that CDCA and FXR agonists improve liver function lead us to investigate whether CDCA and a FXR agonist inhibit HIF-1α function in liver cells." (PMID 26098428, 2015). "HIF1α regulates hundreds of genes, and many of them play a role in cancer metabolism." (PMID 25605240, 2015). "To study whether HIF-1α could directly regulate the NIR dye uptake in canine cancer cells, we treated the cells with a HIF-1α-targeting siRNA (siHIF-1α) against canine HIF-1α gene." (PMID 25361418, 2014). "For the HIF-1α G1790A polymorphism, the pooled results from all of the eligible studies suggested that the G1790A polymorphism in HIF-1α is significantly associated with an increased cancer risk in all of the genetic models." (PMID 25496056, 2014). "HIF-1α is important hypoxia-related factor that is significantly increased after radiotherapy and are closely related with the self-renewal of radioresistant cancer stem cells." (PMID 25485635, 2014). "Because elevated expression of HIF-1α protein has been correlated with drug resistance and overall poor treatment outcome, compounds that inhibit HIF-1α may have broad utility in the control of cancer growth." (PMID 24732040, 2014). "HIF1A expression is critical for cancer cell growth, and its knock-down impairs proliferation." (PMID 24837709, 2014). "Recent studies have demonstrated a critical role of HIF-1α in the maintenance of cancer stem cells." (PMID 25422886, 2014). "Additional studies suggest that mTOR is the upstream regulator of HIF-1α in cancer cells." (PMID 25140303, 2014). "Also demonstrating that aerobic glycolysis is controlled by HIF-1α in IMQ-treated cancer cells, the genetic silencing of HIF-1α reversed the IMQ-enhanced glucose utilization and lactate production." (PMID 24658058, 2014). "Indeed, c-Myc and HIF-1α are well recognized as two master inducers of glycolysis through direct or indirect transactivation of cancer glycolytic genes." (PMID 24738035, 2014). "As with cancer, HIF-1α accumulates, thereby increasing transcription and activity of PDK." (PMID 24363178, 2014). "HIF-1α is thus a critical target for the prevention of cancer progression and distant metastasis." (PMID 24668884, 2014). "The transcription factor HIF-1α plays a key role in regulating the hypoxic response via transcription of a large number of target genes including those involved in glycolysis, particularly those mediating Warburg glycolysis typical of cancer cells." (PMID 24112286, 2014).